ELK3 (ETS transcription factor ELK3)
Diseases named in the same sentence as ELK3 in open-access papers (continued):
Sharing a sentence is not in itself a finding about the gene and the disease.
tumor (36 papers, 2009 to 2025). "Previous research has shown ELK3’s association with tumor invasion and migration." (PMID 40787199, 2025). "Previous studies have indicated that ELK3 can facilitate tumor progression, encompassing aspects like invasion and migration." (PMID 40787199, 2025). "ELK3 is also involved in other important oncogenic processes such as development of peritumoral lymphatic vessels, which is critical for tumor dissemination." (PMID 39930469, 2025). "The transcriptional programs regulated by TBX21, ZNF595, FOSL2, ZNF83, ZNF484, IKZF2, and ELK3 were found to be significantly activated in tumor-reactive T cells." (PMID 39243082, 2024). "IHC analysis revealed that ELK3 protein levels were significantly higher in tumor tissues compared to the normal tissues surrounding tumors." (PMID 38632244, 2024). "This connection between Mid51 and ELK3 has a significant impact on mitochondrial dynamics, which in turn affects the anti-tumor effectiveness of NK cells for treating TNBCs." (PMID 37669960, 2023). "Abnormalities of the ubiquitin-proteasome system are key in PAAD pathogenesis, and the ubiquitin-proteasome UCHL5 can promote tumor progression and dry expression depending on involvement of the ELK3 protein." (PMID 37396042, 2023). "Elk-3 can be phosphorylated and activated by the Ras-Erk signal pathway, and participate in angiogenesis, wound healing, tumor growth, cell adhesion, migration, and invasion." (PMID 36936533, 2023). "ELK3 is highly expressed in a variety of cancers, including basal-like malignant breast cancer, and coordinates metastasis during tumor progression." (PMID 36243865, 2022). "Many studies have reported that ELK3 is overexpressed in a variety of cancer cells and involved in tumor cell metastasis, angiogenesis and malignant evolution." (PMID 34976781, 2021). "Several prior studies have found that ELK3 is overexpressed in cancer cells and is involved in tumor cell transfer, angiogenesis, and malignant evolution." (PMID 34976781, 2021). "In squamous cell carcinoma (SCC), ELK3 knockdown severely impairs tumor growth and prohibits progression from benign papillomas to SCC." (PMID 34409034, 2021). "In order to study the effects of ELK3 knockdown on tumor growth in vivo, we generated xenograft subcutaneous tumors in nude mice." (PMID 32104682, 2020). "An examination of tumor cell extravasation 48 h after the tail vein injection revealed that cancer cells were detected in the lungs of the control group and miR-200a plus ELK3 group." (PMID 32414208, 2020). "ELK3 knockdown inhibited tumorigenesis: control cells formed tumor in three mice, while ELK3 knockdown cells only formed tumor in one mouse." (PMID 32104682, 2020). "In this context, ELK3 is a promising candidate for developing an anticancer drug that prevents metastasis by controlling the tumor microenvironment." (PMID 31182803, 2019). "Here, we report that ELK3 expressed in LECs contributes to the dissemination of cancer cells during tumor growth by providing oncogenic miRNAs to tumor cells through exosomes." (PMID 31182803, 2019). "This study shows for the first time that ELK3 expression in LECs contributes to the dissemination of cancer cells during tumor growth by providing oncogenic miRNAs to tumor cells." (PMID 31182803, 2019). "To identify miRNAs from LECs that are regulated by ELK3 and can affect tumor progression, we compared the miRNA profiles of siELK3-transfected LECs with those of siNS-transfected LECs." (PMID 31182803, 2019). "Suppression of ELK3 in LECs diminished the ability of LECs to promote tumor growth and metastasis of MDA-MB-231 in vivo." (PMID 31182803, 2019). "A possible mechanism underlying the discrepancy between in vitro proliferation and in vivo tumor formation is that ELK3 KD show reduced secretion of proteins that communicate with the microenvironment and drive tumor development." (PMID 27556500, 2016).
tumor (continued). "In order to explore the mechanisms by which XRP44X inhibits tumour progression in TRAMP mice, immunohistochemical (IHC) staining of dorsolateral prostates and tumours was performed with anti-Elk3 (PAb-95) and anti-phospho-Elk3 (MAb-2F3) antibodies." (PMID 27427904, 2016). "We found that XRP44X inhibits tumour growth and metastasis with limited toxicity by a mechanism that involves Elk3." (PMID 27427904, 2016). "Additionally, ELK3 suppresses chemotactic cytokines such as CXCL16 to inhibit tumor-infiltrating NK cells." (PMID 39930469, 2025). "Notably, ELK3 protein levels were markedly elevated in the SPOP-mutant tumor tissue compared to the tissue surrounding the normal area." (PMID 38632244, 2024). "It has been reported that the transcriptional regulator ELK3 found in LECs promoted the expression of pro-oncogenic miRNAs and suppressed anti-oncogenic miRNAs, thereby controlling the signaling cargo transferred to tumor cells through exosomes." (PMID 35454874, 2022). "Moreover, suppression of ELK3 in LECs diminished the ability of LECs to promote tumor growth and metastasis, in vivo." (PMID 35454874, 2022). "Then IHC analysis of the TMA confirmed the overexpression of ELK3 in PDAC tumor tissues." (PMID 34409034, 2021). "Besides, the growth of BC cells has been shown to be promoted by ELK1 and ELK3, both of which were the target genes of miR-135a and critical regulators of tumor-suppressive effects induced by miR-135a." (PMID 32670874, 2020). "Since ELK3 has pro-oncogenic activity for both cancer cells and LECs, ELK3 might modulate the tumor microenvironment by fine-tuning communication between LECs and tumor cells." (PMID 31182803, 2019). "In addition, the expression of CD31, a marker of microvessel formation, was significantly lower in ELK3 KD tumors compared to control tumor." (PMID 27556500, 2016). "We showed that the Elk3 member of the Ets family is a potential target for tumour therapy." (PMID 27427904, 2016). "Moreover, in contrast to classical signs of SCCs, including invasion and discontinuous basement membrane, tumors derived from ELK3-deficient SCC-SCs displayed smooth borders and quite continuous anti-laminin 5 immunolabeling at the tumor-stromal border." (PMID 26590320, 2015). "However, although the important role of ELK3 in tumor progression is well-known, the molecular mechanisms involved in the regulation of ELK3 protein degradation through ubiquitination remain largely unknown." (PMID 38632244, 2024). "It is unclear whether ELK3 functions as a tumor promoter or as a tumor suppressor." (PMID 27556500, 2016). "Thus, we speculate that alterations to the ELK3 KD secretome are related to the formation of smaller tumor masses in the xenograft experiments." (PMID 27556500, 2016). "Relative to scrambled (SCR) control shRNAs, each Elk3 shRNA efficiently knocked down the expression of ELK3 protein in the resulting tumor tissue, and exerted a potent effect, with signs of reduced allograft tumor growth appearing as early as 8–9 days after injection." (PMID 26590320, 2015). "Specifically, we have shown that ELK3 and hsa-miR-155-5p are part of a feedback loop, which may be important for a complete understanding of the cellular response to hypoxia and importantly, comprehension of the hypoxic tumour microenvironment." (PMID 25401928, 2014). "Previous research has suggested that targeting the Ras/ERK-mediated activation of ELK3 with XRP44X, an inhibitor, can suppress tumor growth and metastasis in mice." (PMID 38632244, 2024). "miR-185-5p targets ROCK2, ELK1, ELK3, IGF2, RAGE, BCL2, BCL2L1, and many other genes to suppress tumor cell migration and invasion." (PMID 35223832, 2022). "The results showed that tumors in the sh-ELK3/MIA PaCa-2 group grew more slowly than those in sh-NC/MIA PaCa-2 group, and this phenomenon was also reflected by tumor volume and final tumor weight." (PMID 34409034, 2021).
tumor (continued). "In our study, ELK3 accelerated PDAC cell proliferation, migration, invasion and EMT process in vitro and promoted tumor growth and metastasis in vivo." (PMID 34409034, 2021). "The suppression of ELK3 in MDA-MB-231 cells alters the secretome of cancer cells and results in the inhibition of peritumoral lymphangiogenesis during tumor progression." (PMID 31182803, 2019). "Tumours from XRP44X-treated animals have decreased expression of genes containing Elk3-like binding motifs in their promoters, Elk3 protein and phosphorylated Elk3, suggesting that perhaps XRP44X acts in part by inhibiting the activity of Elk3." (PMID 27427904, 2016). "The oncogenic or tumor-suppressive feature of demethylases may not be determined by overall m6A levels, but rather by m6A dynamics on specific key target genes driving leukemogenesis, such as ELK3, which is evidently not a shared target with ALKBH5." (PMID 40435251, 2025).
cancer (30 papers, 2014 to 2025). A tumor composed of atypical neoplastic, often pleomorphic cells that invade other tissues. "Klf11, which has been reported for its role as an inducer of oligodendroglial cell death downstream of Tgfß signaling and Elk3, which is essential for neural crest development and associated with cancer progression were also highlighted." (PMID 41446274, 2025). "ELK3 has been reported to act as an oncogene in various types of cancer and reside in a risk locus for childhood ALL." (PMID 40435251, 2025). "In terms of regulating metastasis, ELK3 is associated with inhibition of specific genes and microRNAs, expression of which shows an inverse correlation with cancer metastasis." (PMID 39930469, 2025). "Both increased and decreased ELK3 expression have been associated with poor prognosis in different cancer types, indicating its potential as a prognostic indicator." (PMID 37759229, 2023). "Beyond its physiological functions, ELK3 has been associated with various aspects of cancer progression and metastasis, including migration, invasion, EMT, and angiogenesis." (PMID 38188675, 2023). "Several studies have demonstrated that ELK3 is associated with the initiation and progression of various cancers." (PMID 34409034, 2021). "Previous studies from other groups have shown that ELK3 upregulated in some cancer cells and associated with cell growth, migration, and invasion." (PMID 32104682, 2020). "Our study integrates ELK3 deeper into our understanding of the cellular response to oxygen and underlines its importance in cellular processes and cancer." (PMID 25401928, 2014). "In this context, the conceptual novelty of the current investigation lies in the first demonstration of ELK3’s role in suppressing a gene associated with actin cytoskeleton organization, which is a critical determinant of the mechanical integrity of cancer cells." (PMID 39930469, 2025). "Another crucial aspect discussed in this study is the pleiotropic activity of ELK3 in relation to cancer metastasis and immunosensitivity." (PMID 39930469, 2025). "A consistent presence of GFP positive cancer cells was observed of lung tissue from each group of mice, indicating that the ELK3-CYFIP2 axis influences the response of MDA-MB-231 cells to the anti-cancer activity of NK cells in vivo." (PMID 39930469, 2025). "To further validate these findings, we examined the effect of the ELK3-CYFIP2 axis on cancer cell survival in immune-competent mice, both in the presence and absence of NK cells." (PMID 39930469, 2025). "By regulating angiogenic factors like VEGFC, ELK3 promotes growth of lymphatic vessels, thereby facilitating cancer metastasis." (PMID 39930469, 2025). "Regarding regulation of the immune responses or chemoresistance of TNBCs, studies report that ELK3 renders cancer cells resistant to NK cells and cisplatin (CDDP) chemotherapy by regulating mitochondrial dynamics." (PMID 39930469, 2025). "Accumulating evidence demonstrates that the activity regulation of ELK3, a member of the E26 transformation-specific oncogene family, is critical to regulating cell proliferation, migration, and survival in human cancers." (PMID 38632244, 2024). "While previous research has indicated that hypoxia induces ELK3 ubiquitination and degradation through the proteasome, the precise mechanisms and implications of this process in cancer development have yet to be fully elucidated." (PMID 38632244, 2024). "Our previous research has elucidated that the induction of c-fos expression by ELK3 plays a pivotal role in cell transformation and cancer cell proliferation." (PMID 38632244, 2024). "ELK3 is a transcription factor that plays a crucial role in regulating various cellular processes, including cancer metastasis." (PMID 38188675, 2023). "Previously, we reported that ELK3 increases the sensitivity of TNBC cells to the cytotoxicity of natural killer cells by regulating cancer cell mitochondrial dynamics." (PMID 37422450, 2023).
cancer (continued). "ELK3 can modulate genes related to cell proliferation, survival, angiogenesis, and metastasis, which are crucial processes in cancer development." (PMID 37759229, 2023). "Alterations in ELK3 expression have been observed in various cancers, and its expression levels have been investigated as potential prognostic markers." (PMID 37759229, 2023). "Alongside established transcriptional repressors like Snail and ZEB1, emerging factors like HIF1α and ELK3 have been identified as transcriptional regulators of E-cadherin, particularly in the context of cancer." (PMID 38188675, 2023). "ELK3 is a transcription factor that can cooperate with numerous partners to control cancer metastasis." (PMID 35409069, 2022). "ELK3, a member of the ternary complex factor (TCF), has been associated with the initiation and progression of various cancers." (PMID 34409034, 2021). "ETS transcription factor ELK3 (ELK3), a novel oncogene, affects pathological processes and progression of many cancers in human tissues." (PMID 34976781, 2021). "Altogether, these findings indicate that ELK3 regulates cancer progression through different mechanisms of different cell types." (PMID 32104682, 2020). "Several studies have showed that ELK3 is overexpressed in some cancer cells and correlates with cell migration and invasion." (PMID 32104682, 2020). "ELK3 expression is associated with malignancy of various cancers including TNBC, and is expected to be a putative molecular target to prevent cancer progression." (PMID 32414208, 2020). "Cancer driver genes namely CBL, GFI1, RASGRF2 and ELK3 were significantly down-regulated and associated with the significantly down-regulated lncRNAs -T216482, -T334719, -T217484 and -T265137 respectively." (PMID 31324852, 2019). "Taken together, these results indicate that a novel RSK2/ELK3 signaling axis, by enhancing c-Fos-mediated AP-1 transactivation activity, has an essential role in cancer cell proliferation and colony growth." (PMID 31018569, 2019). "We selected for further study the MIR155HG (BIC) gene, which produces a hypoxamir that is involved in processes similar to ELK3, including cancer and angiogenesis." (PMID 25401928, 2014). "Bioinformatic analysis of cancer RNA-seq data shows that hsa-miR-155-5p and ELK3 expression are significantly anti-correlated, as would be expected from hsa-miR-155-5p targeting ELK3 RNA." (PMID 25401928, 2014). "ELK3 and hsa-miR-155-5p are predicted to be involved in related processes, including pathways in cancer (KEGG pathway) and angiogenesis (PANTHER pathway; Tables 1and2)." (PMID 25401928, 2014). "ELK3-DNA binding sites are preferentially located near genes involved in “pathways in cancer” (KEGG; Kyoto encyclopedia of genes and genomes) and “angiogenesis” (PANTHER; protein analysis through evolutionary relationships)." (PMID 25401928, 2014). "In UCEC cancer samples compared to normal, there are lower levels of ELK3 and higher levels of hsa-miR-155-5p." (PMID 25401928, 2014). "This indicates that the ELK3-CYFIP2 axis may influence the sensitivity of cancer cells to NK cell-mediated cytotoxicity, particularly in the context of Arp2/3 activation through LPA." (PMID 39930469, 2025). "Furthermore, in gastric cancer, ELK3 governs the expression of genes related to extracellular matrix remodeling, thus facilitating the dissemination of cancer cells." (PMID 38188675, 2023). "TFPI, TNC, and ELK3 are less studied in OV, but have been well researched in other cancer." (PMID 37759229, 2023). "Considering that mitochondria have a multitude of functions within eukaryotic cells, it is likely that the significance of the ELK3-mediated regulation of mitochondrial dynamics could extend beyond the immune response of cancer cells." (PMID 37422450, 2023). "Besides amplifications, gene fusions involving ELK3, a transcription factor with a multifaceted role in cancer and immune infiltration, were enriched in the medium and high TIL groups." (PMID 33980253, 2021).